KDM4B (lysine demethylase 4B)
Diseases named in the same sentence as KDM4B in open-access papers (continued):
Sharing a sentence is not in itself a finding about the gene and the disease.
infection (4 papers, 2019 to 2025). The state of being infected such as from the introduction of a foreign agent such as serum, vaccine, antigenic substance or organism. "The increased level of p-c-Jun was confirmed in infected pLKO cells, but much less in KDM4B-knockdown cells at 60 min and 120 min post-infection by western blotting." (PMID 30683841, 2019). "Infected KDM4B-depleted cells also exhibited a significantly reduced wound healing effect at 16-h post-infection." (PMID 30683841, 2019). "Infection with H. pylori significantly increased the occupancy of KDM4B and c-Jun." (PMID 30683841, 2019). "Infection of KDM4B-knockdown cells with WT H. pylori greatly reduced the levels of phosphorylated CagA as compared with those of uninfected control cells, suggesting that KDM4B is crucial for the translocation of CagA into infected cells." (PMID 30683841, 2019). "Interestingly, infection with H. pylori induced the expression of both KDM4B and ITGAV, thereby augmenting the propagation of CagA signaling, phosphorylation of c-Jun, and activation of IL-8 expression via the KDM4B-c-Jun complex upon H. pylori infection." (PMID 30683841, 2019). "Interestingly, infection with H. pylori induced an increase in KDM4B production." (PMID 30683841, 2019). "Infection with H. pylori significantly increased the recruitment of both KDM4B (p < 0.01) and c-Jun (p < 0.05) as compared with that in non-infected control cells." (PMID 30683841, 2019).
brain diseases (3 papers, 2017 to 2024). "rs12185519 was mapped to KDM4B, which has the potential to inhibit brain diseases such as AD by blocking ICAM1 and VCAM1‐induced extravasation." (PMID 39300745, 2024). "Our data suggest the potential of KDM4B inhibition for brain disease such as AD by blocking ICAM1 and VCAM1-induced extravasation." (PMID 28327608, 2017). "Thus, blocking ICAM1 or KDM4B could offer a novel therapeutic opportunity treating brain diseases." (PMID 28327608, 2017).
neurodevelopmental disorder (2 papers, 2016 to 2019). A behavioral and cognitive disorder with onset during the developmental period that involves impaired or aberrant development of intellectual, motor, or social functions. "Neuron-specific KDM4B knockout mice displayed neurodevelopmental disorders including spinal malformations and hippocampal impairment." (PMID 30759871, 2019). "This Kdm4b knockout model provides a novel system for neurodevelopmental disorder in vivo investigations." (PMID 30759871, 2019).
hematological tumor (1 paper, 2019). "Recent bodies of work have characterized the contributions of KDM4B to tumorigenesis in both solid and hematological tumor types." (PMID 30759871, 2019). "This suggests that inhibiting KDM4B in hematological cancers may have conflicting outcomes, depending on the tumors being treated." (PMID 30759871, 2019).
KDM4B also shares sentences with these, for which no sentence is quoted: lung adenocarcinoma (3 papers); acute lymphoblastic leukemia (2); cervical squamous cell carcinoma (2); medulloblastoma (2); non-small cell lung carcinoma (2); ovarian serous adenocarcinoma (2); ovarian serous cystadenocarcinoma (2); steatosis (2); triple-negative breast carcinoma (2); adenocarcinoma (1); Adrenocortical Cancer (1); Aicardi-Goutieres syndrome (1); atrophic gastritis (1); attention deficit-hyperactivity disorder (1); Autoimmunity (1); brain glioma (1); brain tumors (1); cholangiocarcinoma (1); chronic gastritis (1); chronic lymphoid leukemia (1); colon adenocarcinoma (1); colorectal adenocarcinoma (1); diffuse large B-cell lymphoma (1); Digestive Disease (1); endocervical adenocarcinoma (1); epilepsy (1); esophageal adenocarcinoma (1); gastric adenocarcinoma (1); gastritis (1); head and neck squamous cell carcinoma (1).
A further 18 diseases each share a sentence with KDM4B in 1 paper.